LIF (LIF interleukin 6 family cytokine)
Diseases named in the same sentence as LIF in open-access papers (continued):
Sharing a sentence is not in itself a finding about the gene and the disease.
adenomyosis (11 papers, 2012 to 2025). The growth of endometrial tissue inside the muscular wall of the uterine corpus. "Downregulation of endometrial LIF mRNA and protein observed in women with adenomyosis and unexplained infertility was associated with affected receptivity." (PMID 32933042, 2020). "Subsequent analysis revealed a distinct decrease in the expression of decidualization marker HAND2 and endometrial receptivity marker LIF in the adenomyosis model." (PMID 39794729, 2025). "Research has suggested that macrophage-derived-LIF significantly decreased in both the endometrium and uterine flushing fluid during the window of implantation in women with adenomyosis-related infertility." (PMID 39966111, 2025). "Our transcriptomic analysis identified TNFAIP6, matrix metalloproteinase 7 (MMP7), TNFAIP3, leukemia inhibitory factor (LIF), and serum and glucocorticoid-regulated kinase 1 (SGK1) as the top 5 genes implicated in the inflammatory mechanisms of adenomyosis." (PMID 40989079, 2025). "Menstrual-phase glands from adenomyosis patients also showed a significantly higher expression of LIF than those from healthy tissues (p = 0.0446)." (PMID 39274229, 2024). "Eutopic endometrium from adenomyosis patients is characterized by an abnormal expression of a number of receptivity markers, namely PR, LIF, HOXA10 and osteopontin." (PMID 39274229, 2024). "Leukemia inhibitory factor (LIF) has been demonstrated to be dysregulated in women with adenomyosis, thus impairing implantation." (PMID 37763670, 2023). "Our data showed significant upregulation of LIF—a glycoprotein cytokine involved in decidualization and immune response —in secretory and gestational adenomyosis organoids compared with control." (PMID 35207707, 2022). "LIF expression was found to be very high in menstrual epithelium from adenomyosis patients, significantly higher than that during the proliferative (p = 0.0034) or secretory (p = 0.0393) phases in the adenomyosis group." (PMID 39274229, 2024). "SPP1, PAEP, LIF, and 17βHSD2 expression were upregulated in adenomyosis sec- and gest-organoids compared with control organoids, indicating possible molecular mechanisms involved in adenomyosis-impaired implantation and pregnancy disorders." (PMID 35207707, 2022). "However, in adenomyosis, the overactivation of M2 macrophages, combined with the ongoing inflammatory response, may impair LIF production or its regulatory functions, indirectly compromising the endometrial receptivity needed for successful implantation." (PMID 39966111, 2025). "As LIF has a multifaceted role in human reproduction ranging from promoting stromal decidualization to facilitating blastocyst implantation and subsequent development, its dysregulation may compromise any of these processes and hence drastically affect reproductive outcomes in adenomyosis patients." (PMID 39274229, 2024). "Adenomyosis organoids showed higher expression of TGF-β2 and SMAD3 and increased gene expression of SPP1, PAEP, LIF, and 17βHSD2 compared with control organoids." (PMID 35207707, 2022). "Isolated total RNA from endometrial biopsy samples collected during the window of receptivity were used to verify whether selected candidate genes LIF, SOCS3, FOS, JUNB, IL6 and IL10 were differentially expressed between adenomyosis and control groups." (PMID 32933042, 2020). "Additionally, LIF and SGK1, known for their roles in implantation and immune modulation, may offer insights into fertility outcomes in adenomyosis patients." (PMID 40989079, 2025). "In the stroma, LIF immunostaining was stronger in secretory-phase endometrium than in proliferative (p = 0.0381) or menstrual (p = 0.0499) endometrium in healthy controls, but this trend was not maintained in the case of adenomyosis." (PMID 39274229, 2024).
adenomyosis (continued). "Indeed, we observed an increase in LIF immunostaining in healthy subjects progressing from the proliferative to the secretory phase, but this was not witnessed in adenomyosis, where the stromal LIF expression was significantly weaker than that in healthy endometrium." (PMID 39274229, 2024). "Despite LIF, IL6, IL10, JUNB, FOS and SOCS3 showing no statistically altered expression patterns between study groups, their lower expression levels were observed in the adenomyosis group." (PMID 32933042, 2020).
breast tumors (11 papers, 2007 to 2023). "It has been reported that LIF and LIF-R expression in breast tumors is associated with favorable biological features such as diploidy and low S-phase fraction." (PMID 17925034, 2007). "Notably, the LIF protein level of these breast tumors was positively associated with glucose uptake reflected by the intensity of 18F-FDG PET scan in breast tumors." (PMID 35440095, 2022). "Notably, high LIF levels are also associated with increased glucose uptake in human breast tumor tissues." (PMID 35440095, 2022). "Especially, ENPP2 was significantly correlated with “IL-6 cytokine receptor ligand interactions”, “LIF signaling 1 up”, “TGFβ receptor signaling” and “prolactin signaling pathway” in human breast tumors." (PMID 37296899, 2023). "Knockdown of Glut1 or blocking AKT signaling by inhibitors largely abolished the promoting effect of LIF on glucose uptake, glycolysis as well as its promoting effect on the growth of xenograft breast tumors." (PMID 35440095, 2022). "The LIF protein levels of breast tumor specimen from these patients were determined by immunohistochemistry (IHC) staining assays." (PMID 35440095, 2022). "We investigated the LIF expression by CAFs since LIF secretion by CAFs in the breast tumor microenvironment is unclear." (PMID 34947829, 2021). "In mouse breast tumors, a high level of LIF expression and activated STAT3 signaling have been observed, resulting in increased tumor cell viability." (PMID 34947829, 2021). "The blockade of TIM-3 in breast tumor explants downregulated genes related to cancer pathways, including those associated with tumor cell proliferation/migration/invasion (WNT5A, LIF, XDH2, SNAI, CDH2, ADAMST12, PLAU, and CDK14)." (PMID 32616706, 2020). "Development of the breast tumors was observed in all the control mice, while the tumors appeared in 75% of animals in the LIF group." (PMID 32651426, 2020). "Since LIF gene expression was confirmed in these cells and derived breast tumors, we studied the effect of LIF immunization on tumor development." (PMID 32651426, 2020). "The expression levels of LIF were determined in the tissue microarray containing the breast tumor tissues from these patients by using IHC staining." (PMID 24553191, 2014). "We further tested whether Wortmannin treatment blocks the promoting effect of LIF on the growth of xenograft breast tumors." (PMID 35440095, 2022). "The activation of the AKT pathway by LIF was also observed in xenograft breast tumors." (PMID 24553191, 2014). "Furthermore, given the effect of LIF expression on the AKT-mTOR signaling, this pathway may serve as a novel therapeutic target to improve outcomes in breast tumors with LIF overexpression." (PMID 24553191, 2014). "Similarly, IL-6 cytokine leukemia inhibitory factor (LIF), which belongs to the IL-6 family of cytokines, was recently identified as a critical factor in cancer progression, metastasis, stem cell maintenance and therapy resistance, and represented as a breast tumor and lung metastasis suppressor." (PMID 34490085, 2021). "In this study, we investigated the consensus of LIF and LIFR immunization on the growth of breast tumors after transplantation of the BTICs into breast fat-pad." (PMID 32651426, 2020). "We further investigated the effect of LIF overexpression on the growth of xenograft breast tumors with or without endogenous Glut1 knockdown." (PMID 35440095, 2022). "Expression of LIF and LIFR by the breast tumors were studied." (PMID 32651426, 2020). "Hence, in this study, we investigated the consensus of LIF and LIFR immunization on the development of breast tumors in mice." (PMID 32651426, 2020).
lung carcinoma (11 papers, 2013 to 2025). "A new lung cancer susceptibility locus located downstream of LIF were found through genome-wide association studies in Han Chinese." (PMID 28952053, 2018). "Specifically, in the context of lung cancer, bone marrow‐derived mesenchymal stem cells secrete LIF, which subsequently engages the LIFR/p‐ERK/pS727‐STAT3 signaling pathway, thereby modulating the balance between EMT and its reverse process, MET." (PMID 40416597, 2025). "In head and neck as well as lung carcinomas, LIF is produced by tumor cells and induces fibroblast activation in a paracrine manner to promote an invasive TME15." (PMID 38789520, 2024). "In summary, downregulation of miR-29c expression promotes muscle catabolism in lung cancer by directly targeting LIF." (PMID 34838029, 2021). "Lewis lung carcinoma (LLC) cell line was used to establish a cachexia model to explore the functions of miR-29c and LIF in lung cancer cachexia." (PMID 34838029, 2021). "The findings showed that LIF is a potential target for miR-29c in lung cancer, and therefore, low plasma levels of miR-29c can be a novel biomarker for cancer cachexia." (PMID 34838029, 2021). "In contrast, miR-500a-3p was significantly associated with longer survival of lung cancer patients and targeted two cancer-associated genes, LIF (leukemia inhibitory factor) and PAPPA (pregnancy-associated plasma protein A, pappalysin 1)." (PMID 28952053, 2018). "LIF and PAPPA, whose expression levels were associated with worse survival of lung cancer patients, were down-regulated in lung cancer H1299 cells after transfection of miR-500a-3p compared to control miRNA mimetic by qRT-PCR." (PMID 28952053, 2018). "LIF is overexpressed in cancerous tissue compared to noncancerous lung and associated with poor outcome in lung cancer." (PMID 39743376, 2025). "Besides, STAT3 is persistently activated in GPCR C5a-knockout (KO) mice, a spontaneous lung cancer developing model, and the use of an antibody against LIF leads to STAT3 inactivation in this model." (PMID 29062084, 2017). "Extracellular vesicles from lung cancer cells can activate the expression of pro-angiogenic factors, including IL-8, VEGF, LIF, oncostatin M, IL-11 and MMP 9 in adjacent stromal cells, “educating” the microenvironment to support lung cancer cell metastasis." (PMID 23908664, 2013). "Together these results suggest that LIF and PAPPA may be biological targets of miR-500a-3p in lung cancer cells." (PMID 28952053, 2018). "Our data reveal LIF and PAPPA as potential targets of miR-500a-3p in lung cancer cells." (PMID 28952053, 2018). "Of note, also the expression levels of other putative tumor-derived cachexia-inducing signaling compounds (OSM, LIF, TNFα, IFNγ, PTHrP, ZAG, PIF, TWEAK, IL-1β, MSTN and INHBA) were tested for possible correlation between expression level and prognosis for lung cancer patients." (PMID 28515477, 2017).
multiple sclerosis (11 papers, 2012 to 2025). A progressive autoimmune disorder affecting the central nervous system resulting in demyelination. "Moreover, promotion of axonal regeneration and oligodendrocyte growth and survival by LIF suggests its potential for reducing damage associated with central inflammatory demyelinating diseases such as multiple sclerosis." (PMID 22894638, 2012). "LIF is increasingly recognized as a potential therapeutic target for multiple sclerosis, as elevated expression of LIF receptor enhances regulatory T cell numbers, thereby contributing to the hyperactive immune system characteristic of the disease." (PMID 40133606, 2025). "In the CNS, astrocytes are considered to be the major source for LIF, and its expression in the brain is significant during pathological conditions including ischemia, multiple sclerosis, Alzheimer’s and Parkinson’s diseases and brain injury." (PMID 22894638, 2012). "It is also reported that LIF is secreted by grafted NSCs and provides protective effects in animal model of multiple sclerosis by promoting survival, differentiation, and the remyelination capacity of both endogenous oligodendrocyte precursors and mature oligodendrocytes." (PMID 27567678, 2016). "LIF production can be regulated by many different factors such as interleukins under different conditions in different tissue/cell types and it has been investigated also in relation to Multiple sclerosis (MS) as a potential therapeutic factor and to neuroinflammatory lesions." (PMID 33034697, 2021). "Likewise, LIF treatment increased the number of differentiated Treg cells by modifying the LIF/IL-6 balance and reducing the symptoms of an autoimmune disease such as multiple sclerosis." (PMID 33330727, 2020). "Finally, LIF was shown to limit demyelination in an experimental autoimmune encephalomyelitis mouse model and has become a prominent therapeutic candidate for multiple sclerosis." (PMID 22894638, 2012). "Although LIF is related to fertility and a series of neurological disorders including multiple sclerosis, recombinant LIF is not used as therapeutic." (PMID 37061565, 2023). "The LIF amount produced by MSCs is not enough, but in literature is reported the use of synthetic stem cells (LIF-Nano) with a 1000-fold greater potency in producing LIF and able to reverse paralysis in preclinical model of multiple sclerosis within 4 days." (PMID 32471272, 2020).
viral infection (11 papers, 2014 to 2024). "LIF is also recognized as a cell-autonomous molecule during intracellular viral infections caused by HIV and HPV." (PMID 36329823, 2022). "In infection models, LIF is recognized as a vital stem cell growth factor that protects the lung from collateral damage during inflammatory attack against viral infections." (PMID 36329823, 2022). "The cytokine LIF, an important antiviral cellular response to viral infection, was upregulated 6.6-fold by PB125." (PMID 32545518, 2020). "We next determined whether the defective primary immune response of LIF-cKO mice to viral infection could be overcome by secondary reinfection 30 days following the original viral challenge." (PMID 39112698, 2024). "In a nutshell, the LIF signal renders both pDCs and late DC progenitors refractory to physiological stimuli controlling pDC functions and development, and, therefore, delays proper immunological response to viral infections, including SARS-CoV-2." (PMID 38455043, 2024). "As previously reported, IRF1 could be induced by many cytokines such as IFNs (-α, -β, -γ), TNF-α, IL-1, IL-6, LIF and virus infection mediated by STAT and NF-κB." (PMID 34930359, 2021). "LIF has not been well investigated in regards to viral infections, but it has been implicated in suppressing the replication of HIV." (PMID 32526950, 2020). "Furthermore, whereas the secondary immune response cleared the virus from the lungs of control mice, the deficit in adaptive immunity in both LIF-cKO mice and ILC2LIFKO mice correlated with persistent viral infection." (PMID 39112698, 2024). "Several newly identified RSV-inducible cytokines (leukemia inhibitory factor (LIF), migration inhibitory factor (MIF), stem cell factor (SCF), CCL27, CXCL12 and stem cell growth factor beta (SCGF-β)) were induced in airways cells in vitro and in mouse lungs during a viral infection in vivo." (PMID 25277705, 2014). "Furthermore, it remains unclear if virus infection and /or replication initiates the upregulation of miR-664 to avoid the antiviral effects of LIF, or if this mechanism is a non-beneficial reaction by the host cell during virus infection." (PMID 27166678, 2016).
hepatocellular carcinoma (10 papers, 2012 to 2025). A malignant tumor that arises from hepatocytes. "The efficiency of LIF-05 in blocking access to the LIFR for other cytokines was proven by the finding that STAT as well as ERK activation in response to both, LIF itself as well as hOSM is strongly impaired upon pretreatment of rat hepatoma cells with LIF-05." (PMID 22937020, 2012). "The increase in ERK1/2 activation upon rOSM stimulation of LIF-05-treated hepatoma cells (lane 10) indicated that the OSMR offers higher affinity binding sites for the activation of this MAPK pathway compared to the LIFR." (PMID 22937020, 2012). "For example, a direct cross talk between Smad3 and STAT3 is bridged by p300 in hepatoma cells, a synergistic action of LIF-induced-Smad1 and BMP2-induced-STAT3 is bridged by p300 in neural cells, and Smad2/3 and STAT3 cooperatively interact in Th17 cell differentiation." (PMID 29963056, 2018). "It elevates miR-192-5p expression through leukemia inhibitory factor (LIF) regulation, effectively inducing autophagy and apoptosis in hepatocellular carcinoma by targeting CYR61." (PMID 40087755, 2025). "Leukemia inhibitory factor (LIF) exerts an oncogenic function in several types of cancer, including hepatocellular carcinoma (HCC)." (PMID 40416597, 2025). "MiR-637 directly targets leukemia inhibitory factor (LIF), which suppresses the tumorigenesis of hepatocellular carcinoma by interfering with the transcription factor Stat3 signaling pathway." (PMID 32264877, 2020). "In this study, miPSCs were treated with the CM derived from hepatocellular carcinoma cell line Huh7 cells, to convert miPSCs into CSCs in the absence of LIF." (PMID 31450740, 2019).
pneumonia (10 papers, 2012 to 2025). An acute, acute and chronic, or chronic inflammation focally or diffusely affecting the lung parenchyma, caused by an infection in one or both of the lungs (by bacteria, viruses, fungi, or mycoplasma.). "LIF in animal models of pneumonia has been identified as a lung-protecting agent since it prevents severe disease development." (PMID 36287942, 2022). "Our study identified the presence of LIF in pneumonia induced PARDS and showed a weak correlation with severity of lung disease (r = 0.52)." (PMID 34239039, 2021). "Consistent with our findings of a MAIT cell tissue repair signature, the LIF has been found to protect against epithelial damage in murine models of pneumonia." (PMID 31533045, 2019). "The LIF is significantly induced during pneumonia and can reduce lung epithelial cell death, promoting the expression of tissue-protective genes essential to lung regeneration and repair and increased mucosal barrier integrity." (PMID 31533045, 2019). "LIF is a prominent STAT3-activating cytokine that facilitates tissue protection during pneumonia and plays a similar airway protective role during RSV infection." (PMID 25277705, 2014). "Leukemia Inhibitory Factor (LIF) can exacerbate airway hyperresponsiveness but may also provide anti-inflammatory benefits during pneumonia; however, its signaling mechanisms remain unclear." (PMID 41226620, 2025). "LIF is an inflammatory mediator that protects the lung during pneumonia." (PMID 39931658, 2022). "LIF is primarily recognized for its ability to preserve the totipotency of embryonic stem cells and is detected in acute respiratory distress syndrome (ARDS) but recently LIF was described to protect the lung from injury during pneumonia." (PMID 25277705, 2014). "Recent research has suggested that induction of an IL-6 cytokine family member, leukemia inhibitory factor (LIF) leads to STAT3 signaling and may control tissue repair in lungs of mice suffering from pneumonia." (PMID 23403960, 2012).